PTGS2 (prostaglandin-endoperoxide synthase 2)
Diseases named in the same sentence as PTGS2 in open-access papers (continued):
Sharing a sentence is not in itself a finding about the gene and the disease.
meningioma (5 papers, 2020 to 2023). A generally slow growing tumor attached to the dura mater. "Furthermore, NF-κB/IL6, PTGS2, MYC/hsa-miR-574-5p, hsa-miR-26b-5p, hsa-miR-335-5p, and hsa-miR-98-5p, which are involved in the transcription factor-miRNA-mRNA coregulation network, were found to be associated with meningioma." (PMID 32832554, 2020).
pancreatic adenocarcinoma (5 papers, 2005 to 2024). "Comprehensive analysis, together with the pancreatic adenocarcinoma (PAAD) dataset from The Cancer Genome Atlas (TCGA), revealed that the ANTXR1, CMTM6, ITGB6, PIGR, and PTGS2 genes were significantly upregulated in GEM‐resistant PDAC cell lines." (PMID 39488785, 2024).
pneumonia (5 papers, 2020 to 2022). An acute, acute and chronic, or chronic inflammation focally or diffusely affecting the lung parenchyma, caused by an infection in one or both of the lungs (by bacteria, viruses, fungi, or mycoplasma.). "IL1B induces the synthesis of prostaglandins (PGs) that affect the pneumonia response, and PTGS2 acts as a key rate-limiting enzyme in the synthesis of PGs." (PMID 33681222, 2021). "Among them, 23 target proteins such as PTGS2, TNF and FOS were enriched in the IL-17 signalling pathway, indicating that the IL-17 signalling pathway plays an important role in the treatment of pneumonia by RYNM." (PMID 33678123, 2021).
prostate tumor (5 papers, 2017 to 2022). "Analysis of these genes in patient samples from the TGCA dataset using the MethHC database (methhc.mbc.nctu.edu.tw) confirmed significant hypermethylation of the DKK3, PTGS2, SLC16A5, HFE, and CYP27A1 promoters in prostate tumors, compared to normal prostate." (PMID 29843383, 2018). "Normal prostate tissues show elevated PTGS2 expression, but prostate tumor tissues show elevated expression or no expression." (PMID 35594510, 2022).
tuberculosis (5 papers, 2021 to 2024). A chronic, recurrent infection caused by the bacterium Mycobacterium tuberculosis. "Combined with our transcriptomic sequencing results, we hypothesize that Mtb-Ag up-regulates PTGS2 by activating the IL-17, TNF, and NF-κB signaling pathways, making the immune response an important tool against tuberculosis." (PMID 37818041, 2023).
adenomyosis (4 papers, 2020 to 2021). The growth of endometrial tissue inside the muscular wall of the uterine corpus. "In a pre-clinical mouse model, prostaglandin D2 genetic deficiency increased endometrial COX2/PTGS2 and PGE2 levels and increased adenomyosis lesion development." (PMID 36304053, 2021).
astrocytoma (4 papers, 2015 to 2022). "Infection with RVFV induced significant upregulation of ATF3, FOS, KLF4, CXCL10, TNF-α, and PTGS2 in astrocytoma cells at 16 hpi." (PMID 35746681, 2022). "Additionally, inhibition of the inflammatory gene PTGS2 with Celecoxib, a small molecule inhibitor, rescued astrocytoma cells from VEEV-induced cell death but had no impact on viral titers." (PMID 35746681, 2022).
autoimmune disease (4 papers, 2006 to 2022). A disorder resulting from loss of function or tissue destruction of an organ or multiple organs, arising from humoral or cellular immune responses of the individual to their own tissue constituents. "The PTGS2 pathway modulates the extend of antiviral response and might play a significant role in autoimmune disease development." (PMID 34943274, 2021).
brain infarct (4 papers, 2005 to 2025). "Inhibition of PTGS2 expression can significantly reduce brain infarct volume and alleviate motor coordination deficits caused by CIS." (PMID 39957706, 2025). "Overexpression of PTGS2 can disrupt the internal environment balance, contribute to the inflammatory response after brain injury, and promote the expansion of the brain infarct area." (PMID 39697434, 2024). "Moreover, functional experiments were executed using sh-PTGS2 transfection, revealing that the volume of cerebral infarction, neurological injure and water content were inhibited following the interference of PTGS2 compared with the MCAO group." (PMID 38198162, 2024). "In clinical applications, early intervention and inhibition of PTGS2 may have certain therapeutic significance for reducing the area of cerebral infarction and neurological damage in IS patients." (PMID 38198162, 2024). "Above all, silencing of PTGS2 could reduce the volume of cerebral infarction and rescue the neuronal damage." (PMID 38198162, 2024).
brain injury (4 papers, 2009 to 2023). Acute and chronic (see also brain INJURIES, CHRONIC) injuries to the brain, including the cerebral hemispheres, CEREBELLUM, and brain STEM. "In contradiction, MIR212-mediated downregulation of PTGS2 mRNA prevents ferroptotic neuronal death in a traumatic brain injury mouse model suggesting a cell type-dependent role of PTGS2 in ferroptosis." (PMID 37996827, 2023). "In contradiction, MIR212-mediated the downregulation of PTGS2 mRNA prevents ferroptotic neuronal death in a traumatic brain injury mouse model, suggesting a cell type-dependent role of PTGS2 in ferroptosis." (PMID 33553189, 2021). "For example, we identified target genes that encode enzymes involved in prostaglandin biosynthesis and in modulating AS activation in response to brain injuries, including Alox5 and Ptgs2." (PMID 19888342, 2009).
colorectal polyps (4 papers, 2007 to 2023). "For the PTGS2 SNP rs2745557, total colorectal polyp risk reduction was restricted to individuals with one or more minor (A) alleles [IRR, 0.60 (0.41–0.88); P = 0.009; pFDR q = 0.06], but not common homozygotes (Pint = 0.2)." (PMID 37756582, 2023). "A previous analysis of the interaction between PTGS2 SNPs and aspirin use related to colorectal polyp recurrence in the Aspirin/Folate Polyp Prevention Study (AFPPS) described a possible interaction between rs4648310 and aspirin use (81 mg daily)." (PMID 37756582, 2023). "The association of PTGS1 SNP rs4837960 and PTGS2 SNP rs2745557 with colorectal polyp risk reduction by aspirin has not been reported previously." (PMID 37756582, 2023). "None of the PTGS1, PTGS2, or HPGD SNP genotypes, including rs4837960 and rs2745557, reached univariate statistical significance for a difference in total colorectal polyp number or adenomatous polyp number between individuals who received either active EPA or placebo EPA." (PMID 37756582, 2023).
cutaneous melanoma (4 papers, 2007 to 2025). A primary melanoma arising from atypical melanocytes in the skin. "Strikingly, mRNA expression levels for IL-6, G-CSF, CXCL1, and other known tumor-promoting inflammatory factors showed strong positive correlation with those of PTGS2 in samples from human cutaneous melanoma." (PMID 26343581, 2015). "A negative correlation of MITF and PTGS2 is also observed in the TCGA dataset for skin cutaneous melanomas." (PMID 32978520, 2020).
cytomegalovirus infection (4 papers, 2019 to 2024). A herpesvirus infection caused by Cytomegalovirus. "Pro-inflammatory mediators such as interleukin (IL)-6 and prostaglandin-endoperoxide synthase 2 (PTGS2, cyclooxygenase-2) promote cancer progression, and can be produced by HCMV infection." (PMID 34575976, 2021).
Epileptic seizures (4 papers, 2014 to 2021). "Consistent with our present work, the level of 4-HNE and PTGS2 mRNA were observed to be remarkably elevated in seizure models." (PMID 33362556, 2020). "Emerging studies have shown that baicalein is a selective inhibitor of ALOX12/15, which in turn strongly downregulates prostaglandin-endoperoxide synthase 2 (PTGS2) and upregulates GPX4, and significantly suppresses ferroptosis to exhibit a neuroprotective role in post-traumatic epileptic seizures." (PMID 35118067, 2021).
fibrosis (4 papers, 2021 to 2024). the formation of excess fibrous connective tissue in an organ or tissue in a reparative or reactive process. "Ptgs2, another marker of ferroptosis, which is rarely found around fibrotic scar regions where robust staining of α-SMA is present, was dramatically enhanced along with downregulation of α-SMA in BBR-treated fibrosis mice." (PMID 34864819, 2021).
insomnia (4 papers, 2019 to 2025). A sleep disorder characterized by difficulty in falling asleep and/or remaining asleep. "We could predict the role of VVO in modulating the serotonergic synaptic pathway in the treatment of insomnia, and this modulation was associated with MAOB, MAOA, PTGS2, HTR2A, and SLC6A4." (PMID 40004189, 2025). "The results from the PPI analysis show that the targets of VVO for the treatment of insomnia mainly involve MAOB, DRD2, MAOA, IL1B, PTGS2, HTR2A, SLC6A4, and ESR1." (PMID 40004189, 2025).
lipid metabolism disorders (4 papers, 2022 to 2025). "At the same time, some studies demonstrated that puerarin could inhibit the expression of ACSL4 and PTGS2 and then reduce lipid peroxidation and regulate lipid metabolism disorder." (PMID 35888777, 2022). "In this study, GA was shown to significantly reduce ferrous ion accumulation and PTGS2 expression, increase GPX4 expression, inhibit excessive ROS production, and attenuate lipid metabolism disorders." (PMID 41415578, 2025). "The reduction and inactivation of STAT3 lead to lipid metabolic disorders and promote triglyceride accumulation by upregulating the mRNA levels of ELOVL7, PPARG, MMP1, MMP13, and TIMP4, and downregulating the mRNA level of PTGS2." (PMID 39125712, 2024). "These targets play an important role in the PPI network and KEGG signaling pathway, and they have a significant impact on glucose, lipid metabolism disorders, and inflammation (such as TNF-α, AKT1, PPARG, and PTGS2)." (PMID 36199550, 2022). "These targets play an important role in the PPI network and KEGG signaling pathway, and they have a significant impact on glucose and lipid metabolism disorders and inflammation (such as TNF-α, AKT1, PPARG, and PTGS2)." (PMID 36199550, 2022).
liver cirrhosis (4 papers, 2018 to 2025). "Cyclooxygenase 2 (COX2), which is also known as prostaglandin-endoperoxide synthase 2 (PTGS2), is the rate-limiting enzyme in prostaglandin biosynthesis and may be involved in liver cirrhosis." (PMID 30134610, 2018).
metastatic tumors (4 papers, 2011 to 2023). "We then analyzed an in-house gene profiling dataset of seven matched metastatic tumor samples obtained from a cohort of patients before therapy and after the onset of treatment resistance for expression values of PTGS2 and of a number of additional direct or indirect miR-146a targets." (PMID 32967672, 2020). "Researchers have been investigating whether inhibiting both the EGFR and PTGS2 (COX-2) signaling pathways at lower doses could yield additive effects on blocking tumor growth and the spread of metastatic disease." (PMID 24213116, 2011).
non-alcoholic fatty liver disease (4 papers, 2021 to 2025). "Portulaca oleracea and its main component, myricetin, alleviate non-alcoholic fatty liver disease by downregulating and inhibiting prostaglandin-endoperoxide synthase 2 (PTGS2)." (PMID 40176886, 2025).
pulmonary diseases (4 papers, 2021 to 2024). "PTGS2, also known to modulate mitochondrial function and lipid metabolism pathways, plays a crucial role in ferroptosis during cardiac and pulmonary disease processes, challenging the traditional view of its sole pro-inflammatory role." (PMID 38549670, 2024). "However, there are no reports specifically addressing the role of PTGS2 in HIV-related pulmonary diseases." (PMID 39192637, 2024).
small cell lung carcinoma (4 papers, 2017 to 2023). Small cell lung cancer (SCLC) is a highly aggressive malignant neoplasm, accounting for 10-15% of lung cancer cases, characterized byrapid growth, and early metastasis. "Enrichment analysis indicated that PTGS2 was involved in the regulation of biological process and small cell lung cancer." (PMID 27765529, 2017). "Furthermore, PTGS2 was directly enriched in related inflammation pathways, such as the TNF signaling pathway and the IL-17 signaling pathway, and in small cell lung cancer." (PMID 34211564, 2021).
systemic sclerosis (4 papers, 2016 to 2025). A chronic disorder, possibly autoimmune, marked by excessive production of collagen which results in hardening and thickening of body tissues. "The down-regulation of PTGS2 is related to abnormal immunocyte infiltration and the occurrence of interstitial lung disease in systemic sclerosis (SSc-ILD)." (PMID 40149697, 2025).
uveal melanoma (4 papers, 2007 to 2021). A melanoma derived from melanocytes of the uveal tract. "Taken together, these data indicate that PTGS2 may be a potential therapeutic target for uveal melanoma treatment." (PMID 34124047, 2021).
vitiligo (4 papers, 2021 to 2023). Generalized well circumscribed patches of leukoderma that are generally distributed over symmetric body locations and is due to autoimmune destruction of melanocytes. "The upregulated genes in vitiligo lesional skin include markers of inflammation (such as MARCO, NLRP10, PTGS2, and IL36G), oxidative response genes (DUOXA2), and NK cell receptors (NCR3LG1), revealing presence of activated immune response in vitiligo lesions." (PMID 33815367, 2021).
acute myeloid leukemia (3 papers, 2007 to 2025). Acute myeloid leukemia (AML) is a group of neoplasms arising from precursor cells committed to the myeloid cell-line differentiation. "Of those genes, BCL2 and PTGS2 were shown to be upregulated in acute myeloid leukemia." (PMID 34422220, 2021). "Although GEPIA indicated PTGS2 upregulation in acute myeloid leukaemia (AML), no data was available for CML." (PMID 40444088, 2025).
allergic rhinitis (3 papers, 2019 to 2024). Inflammation of the nasal mucous membranes caused by an IgE-mediated response to external allergens. "The study involved molecular docking analysis of berberine with five key genes (Alb, Il6, Il1b, Tlr4, and Ptgs2) to validate its potential targets against allergic rhinitis." (PMID 38796469, 2024). "Furthermore, the MCODE plugin was employed to pinpoint 14 genes (Cyba, Nfkbia, Fos, Mpo, Il6, Il1b, Sele, Vcam1, F2, Tlr4, Alb, Egr1, Smad3, and Ptgs2) forming a primary cluster, potentially representing a crucial regulatory network for berberine in treating allergic rhinitis." (PMID 38796469, 2024).
amoebiasis (3 papers, 2017 to 2022). "For example, lncRNA BX470102.1 is involved in amoebiasis, Kaposi sarcoma-associated herpesvirus infection, TNF signaling pathway, and IL-17 signaling pathway by targeting multiple target genes such as IL-6, CXCL2, and PTGS2." (PMID 36457749, 2022).
bladder tumor (3 papers, 2019 to 2022). "More importantly, significant PTGS2 immunofluorescence is observed in PAA4- and PAA5-treated groups, verifying the cluster-induced ferroptosis in bladder tumor." (PMID 35945240, 2022).
chorioamnionitis (3 papers, 2014 to 2025). A morphologic finding indicating inflammation of the fetal sac membranes. "Increased PTGS2 expression induced by cytokines, would explain the upregulation of PTGS2 in the inflamed membranes of chorioamnionitis." (PMID 25048443, 2014). "In the placenta, the existing evidence suggests that there is no change in expression of PTGS2 with gestational age or clinical chorioamnionitis." (PMID 25048443, 2014).
coagulopathy (3 papers, 2011 to 2025). "Analysis of the targets overlapped such as PTGS1, PTGS2, PIK3CG, and PECAM1 in the pathological processes of hemorheological abnormality and coagulopathy implied that inflammation and immunity were also important for QS-BSS which need further study." (PMID 32190085, 2020).
ductal carcinoma in situ (3 papers, 2011 to 2020). "Studies have shown that PTGS2 is upregulated in approximately 40% of BC patients (including ductal carcinoma in situ and invasive cancer) and associated with metastasis diseases, which reduced patients' survival rate." (PMID 32849897, 2020).
Dysmenorrhea (3 papers, 2023 to 2025). Pain during menstruation that interferes with daily activities. "In addition, studies have shown that PTGS2 increases the risk of pain in women with EMs, and the cyclooxygenase II (COX-2) enzyme, encoded by the PTGS2 gene, is naturally induced by aromatase and is involved in the conversion of arachidonic acid to prostaglandins, which may induce dysmenorrhea." (PMID 36817586, 2023). "Six essential oil components could be associated with chronic pain, acute pain, musculoskeletal pain, visceral spasms, and dysmenorrhea by acting on four protein targets, including CHRM1, PTGS1, PTGS2, and SLC6A2." (PMID 40729010, 2025).
dyspepsia (3 papers, 2015 to 2023). An uncomfortable, often painful feeling in the stomach, resulting from impaired digestion. "Notably, PTGS1 and PTGS2 exhibited the strongest associations with functional dyspepsia." (PMID 37375548, 2023). "Fourteen genes corresponding to two gene sets were identified, and the functional dyspepsia-related genes targeted by the activated F. fructus compound were ADRA2A, BDNF, CCK, CRP, GCG, JUN, Kcnh2, PTGS1, PTGS2, Pyy, SLC6A4, and TRPV." (PMID 37375548, 2023). "In addition, it was found that there was a therapeutic effect on functional dyspepsia through a mechanism related to the interaction between seven major active ingredients of F. fructus, such as oleic acid and β-sitosterol, and 12 functional dyspepsia-related genes, including PTGS1 and PTGS2." (PMID 37375548, 2023).
endometrial neoplasm (3 papers, 2011 to 2024). Tumors or cancer of ENDOMETRIUM, the mucous lining of the UTERUS. "In conclusion, NFAT5 is expressed in high-grade endometrial tumor tissue and upregulates many genes including HIF1A and PTGS2, which may participate in malignant tumor pathogenesis." (PMID 38612478, 2024). "PTGS2 expression and PGE2 biosynthesis is elevated in endometrial adenocarcinoma, however the mechanism whereby PTGS and PGE2 regulate endometrial tumour growth is unknown." (PMID 21589857, 2011).
endometrial polyp (3 papers, 2016 to 2023). A benign nodular lesion protruding above the surface of the endometrium. "To determine whether polypectomy influences the expression of implantation-related factors, we examined the effects of excision on the expression levels of the IGFBP1, IGFBP7, PTGS2, and CALR mRNAs in 27 patients with endometrial polyps." (PMID 34638846, 2021).
fibrosarcoma (3 papers, 2007 to 2023). A malignant mesenchymal fibroblastic neoplasm affecting the soft tissue and bone. "Golub-score analysis identified a relatively poor discriminatory signal of 200 genes for the fibrosarcomas, which regardless of high FDR contained several of the upregulated genes previously associated with fibrosarcoma, e.g. BMI1, H1F0, LEF1, RBM4, ITM2A, IGFBP2 and PTGS2." (PMID 17359542, 2007).
gallbladder carcinoma (3 papers, 2013 to 2023). "Multiple polymorphisms in genesassociated with the immune system, inflammation, and oxidative stress that have been linkedto the development of gallbladder cancer like PTGS2, TLR2, TLR4, IL1RN, IL10, IL8, CCR5,LXRB, and OGG1." (PMID 28105075, 2016).
Hepatitis (3 papers, 2013 to 2023). Inflammation of the liver. "In HBV-induced hepatitis, the expressions of MAPK1, PTGS1, PTGS2, PLA2G4A, and TLR4 increased significantly." (PMID 37741847, 2023).
Huntington disease (3 papers, 2015 to 2024). Huntington disease (HD) is a rare neurodegenerative disorder of the central nervous system characterized by unwanted choreatic movements, behavioral and psychiatric disturbances and dementia. "In addition, Ptgs2 is also responsible for the synthesis of inflammation-related PG, and the inhibition of PG and NO production has been proposed as a therapeutic target for inflammatory diseases, such as PD, Huntington’s disease and AD." (PMID 25811458, 2015). "In addition, Ptgs2 is also responsible for the synthesis of inflammation-related PG, and it is believed that the inhibition of PG and NO production might be a therapeutic target for inflammatory diseases such as PD, Huntington’s disease, and AD." (PMID 25890327, 2015).